AGT (angiotensinogen)
Diseases named in the same sentence as AGT in open-access papers (continued):
Sharing a sentence is not in itself a finding about the gene and the disease.
diabetic nephropathy (continued). "We focused on the role of angiotensinogen and oxidative stress in diabetic nephropathy." (PMID 40003909, 2025). "Based on the hypothesis that food antioxidant components affect AGT secretion by the kidney, we asked whether food-derived antioxidants inhibit the development of diabetic nephropathy by decreasing AGT secretion." (PMID 40362266, 2025). "The considered studies show that the intrarenal RAS—especially AGT—plays a diversified role in diabetic nephropathy; for instance, the increase in AGT due to oxidative stress is suppressed by polyphenols with antioxidant capacity, which is thought to affect the progression of diabetic nephropathy." (PMID 40003909, 2025). "Thus, diabetic nephropathy was characterized by increased kidney angiotensinogen expression, evidencing activation of intrarenal RAS." (PMID 36361612, 2022). "In the future, these methods may be useful to investigate the segmental regulation of AGT mRNA and protein expression in physiological and pathological conditions such as diabetic nephropathy." (PMID 22606032, 2012). "Moreover, others and we showed that intrarenal AGT mRNA and/or protein levels are increased in various kidney diseases including diabetic nephropathy, immunoglobin A nephropathy, and radiation nephropathy." (PMID 22606032, 2012). "However, the details regarding how AGT expression and secretion in the kidney are controlled in the progression of diabetic nephropathy remain unclear." (PMID 40003909, 2025). "Thus, normoalbuminuric and normotensive children and adolescents with type 1 diabetes have elevated urinary VEGF, AGT, and transferrin levels, which may indicate the development of diabetic kidney disease before the development of albuminuria." (PMID 40362266, 2025). "However, the mechanism by which kidney angiotensinogen expression and secretion induce the onset and progression of diabetic nephropathy remains unclear." (PMID 40362266, 2025). "Furthermore, through clarifying how the intake of soy isoflavones—which possess antioxidant properties—affects the progression of diabetic nephropathy via AGT in detail, the usefulness of soy isoflavones in slowing or reversing the progression of diabetic nephropathy can be elucidated." (PMID 40003909, 2025). "The purpose of this study was to determine whether antioxidant polyphenols affect AGT expression in the kidney and to clarify the mechanism by which soy isoflavones, which have strong antioxidant properties, suppress diabetic nephropathy progression through AGT expression and secretion." (PMID 40362266, 2025). "However, some studies are also available which contradict these findings and do not show the association between AGT M235T and AGT T174M gene polymorphism and diabetic nephropathy." (PMID 36557328, 2022). "The biomarkers of diabetic nephropathy (MCP-1, AGT, and L-FABP) in standard solutions and urine were quantitatively detected in 2 min." (PMID 34832765, 2021). "The present study has demonstrated, for the first time, that high glucose augments AGT in human RPTCs through HNF-5, which provides a potential therapeutic target for diabetic nephropathy." (PMID 29053707, 2017). "High glucose has been demonstrated to induce angiotensinogen (AGT) synthesis in the renal proximal tubular cells (RPTCs) of rats, which may further activate the intrarenal renin-angiotensin system (RAS) and contribute to diabetic nephropathy." (PMID 29053707, 2017). "Other authors and ourselves have also reported the augmentation of intrarenal AGT expression in streptozotocin-induced type 1 diabetic mice and Zucker Diabetic Fatty (ZDF) type 2 diabetic rats, and in hole renal tissue specimens from patients with diabetic nephropathy." (PMID 24284398, 2013). "Despite the importance of the RAS in the development of diabetic nephropathy, the significance of the intrarenal RAS—especially the role of AGT—in the early stage of type 1 diabetic nephropathy has not yet been fully revealed." (PMID 40003909, 2025).
chronic kidney disease (136 papers, 2006 to 2026). Impairment of the renal function secondary to chronic kidney damage persisting for three or more months. "Angiotensinogen in first-morning urine is associated with a decreased nocturnal melatonin secretion and has been increased in chronic kidney disease, preeclampsia, and gestational diabetes." (PMID 36614302, 2023). "Angiotensinogen is considered as a potential urinary biomarker that identifies humans from group of risk of chronic kidney disease (CKD)." (PMID 32722141, 2020). "Angiotensin I-converting enzyme gene insertion/deletion and angiotensinogen M235T polymorphisms: Risk of chronic renal failure." (PMID 23401650, 2013). "Haplotypes of A>G (-6) – Thr174Met – Met235Thr SNPs in AGT gene tested for association with diabetic chronic renal insufficiency." (PMID 16672053, 2006). "In a mouse of model of 5/6 nephrectomy (an experimental subtotal nephron ablation model of induced chronic kidney disease), mice displayed an increase in urinary/renal levels of renin, AGT, and Ang II." (PMID 39093387, 2024). "In addition, in observational studies, urine AGT elevation is an early marker of diabetic kidney injury and antedates chronic kidney disease." (PMID 36361612, 2022). "Although urinary angiotensinogen (AGT) and renin reflect intrarenal renin-angiotensin system activity and are enhanced in proteinuric chronic kidney disease, the clinical value of urinary AGT and renin levels during antiproteinuric treatment has yet to be determined." (PMID 32410703, 2020). "Moreover, urinary AGT levels were well correlated with renal function and the degree of albuminuria in a wide range of chronic kidney disease population." (PMID 26092580, 2015). "Our findings are suggestive of a role of the RAS in modulating the severity of AKI, a notion which is supported by a recent study in which an association was reported between severity of tubular atrophy and urinary angiotensinogen among individuals with chronic kidney disease." (PMID 23587112, 2013). "We aimed to examine the cross-sectional associations of urinary angiotensinogen (AGT) excretion, a biomarker of intrarenal RAS activity, with central (aortic) and renal hemodynamic parameters in middle-aged and older adults, including patients with chronic kidney disease." (PMID 37460637, 2023). "Thus, subjects carrying the T allele in AGT M235T and the D allele in ACE I/D may have especially high angiotensin II, based on the RAS pathway, and increased risk of chronic kidney disease." (PMID 27045371, 2016). "Visceral adipocytes have been shown to produce an array of adipocytokines that could contribute to endothelial injury in the kidney influencing progression to chronic kidney disease (CKD), such as angiotensinogen, TNF-α, plasminogen activator inhibitor-1, resistin, ghrelin, and leptin." (PMID 31152254, 2019). "In case II, PKD-end-stage renal disease (ESRD), AGT was also expressed in the proximal tubules; however, its intensity was slightly reduced than that of case I. Nevertheless, strong expression of AGT was also noted at cyst-lining epithelial cells in case II." (PMID 26092580, 2015). "Urinary angiotensinogen (UAGT) level has been shown highly correlated with intrarenal renin-angiotensin system (RAS) activity and severity of chronic kidney diseases (CKD)." (PMID 30541470, 2018). "The prognostic value of urinary angiotensinogen (UAGT) in patients with chronic kidney disease (CKD) has not been completely evaluated, although the association of UAGT with renal outcomes has been suggested in specific subsets of CKD." (PMID 36139118, 2022).
preeclampsia (121 papers, 2009 to 2026). Preeclampsia is a hypertensive disorder of pregnancy that is characterized by new-onset hypertension with proteinuria presenting after 20 weeks of gestation, and depending on mild or severe forms may initially present with severe headache, visual disturbances, and hyperreflexia. "We identified that PEGIL11 treatment significantly regulated the placental production of multiple factors previously associated with preeclampsia including alpha-fetoprotein, angiotensinogen, apolipoproteins A1 and B, and vitamin D receptor." (PMID 37292200, 2023). "Some mutations on the R-A-A axis have been associated with preeclampsia, as in the case of the missense mutation in the AGT (angiotensin) gene M235T, which was associated with elevated plasma levels of AGT in carriers of this variant." (PMID 35198246, 2022). "This study shows that pregnant women with gestational hypertension or preeclampsia have increased urinary AGT and potassium excretion associated with signs of glomerular swelling." (PMID 31237175, 2019). "SNPs in the AGT gene are associated with increased levels of AGT and an increased prevalence of preeclampsia." (PMID 31551925, 2019). "Seven alleles were significantly or marginally significantly associated with preeclampsia, which involved six genes (rs4762 in AGT, rs1800896 in IL-10, rs1800629 and rs1799724 in TNFα, rs2070744 in NOS3, rs7412 in APOE, and rs2549782 in ERAP2)." (PMID 30112393, 2018). "Preeclampsia (PE) is a common pregnancy-related complication, and polymorphisms in angiotensinogen (AGT), angiotensin-converting enzyme (ACE), and angiotensin II type 1 receptor (AT1R) are believed to contribute to PE development." (PMID 28698595, 2017). "In our list of pathogenic genes, we should notice the AGT derive from 1) the AT1-AA auto-antibody that interact with AGTR1 or 2) from some polymorphism in AGT that had being associated with increased risk of preeclampsia." (PMID 28789679, 2017). "In conclusion, our findings is in line with several studies in which they have suggested that the presence of M235T angiotensinogen gene polymorphism should be considered and investigated as a risk factor in women with preeclampsia." (PMID 25530769, 2014). "Further recent data underlines the connection between RAS and preeclampsia, since there is an association with a polymorphism of Angiotensinogen in Chinese women." (PMID 24151488, 2013). "The rs3789678 angiotensinogen polymorphism correlated significantly with gestational hypertension." (PMID 38411777, 2024). "Of interest, published research shows that polymorphisms in the angiotensinogen gene in both maternal and fetal DNA could be associated with an increased risk of adverse pregnancy outcomes, including preeclampsia and intrauterine FGR." (PMID 38398716, 2024). "Moreover, the AGT rs7079 TT genotype was associated with increased preeclampsia risk in the recessive model (OR = 4.054, 95% CI = 1.178–13.945, p = 0.026)." (PMID 36836041, 2023). "Given the strong link between REN and AGT, we aimed to assess whether there is a combined effect of feto-placental REN and maternal AGT on risk of preeclampsia in humans." (PMID 20537141, 2010). "Our findings indicate that the mother's AGT haplotypes affect her risk for developing preeclampsia." (PMID 20537141, 2010). "We found a significant association between maternal AGT haplotypes and preeclampsia in our data." (PMID 20537141, 2010). "The important role RAS plays in pregnancy is further underlined by the fact that a preeclampsia-like model has been generated in female mice transfected with the human angiotensinogen gene and mated with males transfected with the human renin gene underlines this role." (PMID 19646248, 2009). "Therefore, our objective was to determine whether the genes for placental renin (REN) and maternal angiotensinogen (AGT) interact to influence the risk of preeclampsia." (PMID 20537141, 2010).
preeclampsia (continued). "A preclinical report concluded an siRNA reducing maternal hepatic angiotensinogen expression rescued a preeclampsia phenotype in two animal models and even improved placental morphology." (PMID 40497429, 2025). "The main findings of this study are the high angiotensinogen and low melatonin levels in the urine of women with gestational diabetes or preeclampsia." (PMID 35309508, 2022). "For early diagnosis of gestational diabetes or preeclampsia, morning void urine angiotensinogen-melatonin-creatinine ratio is suggested." (PMID 35309508, 2022). "Using multivariable adjusted models, we will be able to assess the impact of other factors on the reported correlations between altered urine angiotensinogen or melatonin levels and gestational diabetes and preeclampsia." (PMID 35309508, 2022). "It appears that additional research is necessary to determine the relevance of urinary angiotensinogen in the detection of preeclampsia." (PMID 35309508, 2022). "The presence of elevated angiotensinogen and low 6-sulfatoxymelatonin in the first morning void urine samples of patients with gestational diabetes or preeclampsia suggests activation of the intrarenal RAS and an impairment in melatonin synthesis." (PMID 35309508, 2022). "In this pilot study, we use a transgenic mouse model that chronically overexpresses human angiotensinogen and renin (R+A+ mice) that displayed characteristics of preeclampsia such as proteinuria during gestation." (PMID 33584345, 2021). "An interaction between the AGT T704C and ACE I/D polymorphisms and the risk of severe preeclampsia or the time onset of PE were observed, but these were not analyzed in any former meta-analysis." (PMID 33230614, 2020). "Our meta-analysis demonstrated that the polymorphisms of AGT T704C and ACE I/D were significantly associated with an increased risk of preeclampsia (PE) and weak associations of the AT1R A1166C polymorphism with PE were observed." (PMID 33230614, 2020). "The interaction between renin and oxidised AGT, which is present in excess in the plasma of women with preeclampsia, is accelerated in the presence of s(P)RR, which is also increased in preeclampsia." (PMID 31551925, 2019). "Substantial promise for a CD28 superagonist treatment was demonstrated in a rat model of preeclampsia induced by overexpression of human angiotensinogen." (PMID 30984163, 2019). "Investigations of a role for the intrarenal RAS and, in particular, for AGT during pregnancy are in their infancy, although many roles both in pregnancy and preeclampsia have been suggested for the placental and circulating RAS." (PMID 31237175, 2019). "Consistent with a critical role for peri-implantation Treg cells, a genetic model of preeclampsia involving overexpression of human angiotensinogen and renin in rats showed greater responsiveness to Treg cell therapy when it was applied in early gestation." (PMID 30984163, 2019). "Levels of both oxidised and reduced AGT are increased in the plasma of women with preeclampsia as are levels of s(P)RR." (PMID 31551925, 2019). "It is thought that administration of magnesium in the treatment of preeclampsia possibly reduces the activity of plasma renin and angiotensin converting enzymes resulting in low levels of renin, angiotensinogen, angiotensin II, and aldosterone." (PMID 30155474, 2018). "We tested the effects of relaxin in a transgenic rat model of preeclampsia, which is generated by mating female rats transgenic for human angiotensinogen with rats transgenic for human renin." (PMID 26963382, 2016). "It has been shown that the angiotensinogen redox switch is reduced in plasma from healthy individuals and oxidized in plasma from preeclampsia patients." (PMID 25237187, 2014). "Three haplotype-tagging SNPs (htSNPs) covering REN (rs5705, rs1464818, and rs3795575) and another three covering AGT (rs2148582, rs2478545 and rs943580) were genotyped in 99 mother-father-child triads of preeclampsia pregnancies." (PMID 20537141, 2010).
preeclampsia (continued). "Specifically, preeclampsia-like symptoms were observed when females carrying human AGT were mated with males carrying human REN, whereas pregnant mice derived from other mating combinations did not manifest preeclamptic symptoms." (PMID 20537141, 2010). "We found an association between maternal AGT haplotypes and preeclampsia, and a weak association between fetal REN and preeclampsia." (PMID 20537141, 2010). "Women with preeclampsia had reduced placental and urinary Na+ concentrations, yet increased urinary angiotensinogen and reduced active renin, aldosterone concentrations, and osmotic response signal TonEBP (tonicity-responsive enhancer binding protein) expression." (PMID 38966986, 2024). "Since our study is cross-sectional, assigning causality between the altered urinary angiotensinogen or melatonin levels and pathogenesis of gestational diabetes and preeclampsia is not possible." (PMID 35309508, 2022). "In this observational clinical study, we hypothesized that alterations in urinary melatonin or angiotensinogen levels may be altered in two common conditions, preeclampsia and gestational diabetes." (PMID 35309508, 2022). "These may imply a time-dependent activation/suppression of the renal renin-angiotensin system during preeclampsia, as measured by urine angiotensinogen/creatinine levels." (PMID 35309508, 2022). "Additionally, the urine angiotensinogen-6-sulfatoxymelatonin ratio was elevated in women with gestational diabetes or preeclampsia." (PMID 35309508, 2022). "Some data suggest an association between the single nucleotide polymorphisms AGT T704C, ACE I/D, and AT1R A1166C and preeclampsia, but overall, the data are conflicting; the aim of our study was to discover a more stable and reliable association between these polymorphisms and PE risk." (PMID 33230614, 2020). "Surprisingly, unlike other causes of proteinuria, preeclampsia is associated with a reduction in the urinary excretion of AGT." (PMID 31551925, 2019). "Since (P)RR increases the catalytic activity of renin with oxidised AGT and levels of both s(P)RR and oxidised AGT are increased in preeclampsia, the increased release of s(P)RR could contribute to the dysregulation of maternal RASs in preeclampsia." (PMID 31551925, 2019). "With the knowledge that pregnancy is the most common cause of acute kidney injury in women of childbearing age, the urgency to monitor disease progression in preeclampsia, possibly by urinary AGT as a marker of inappropriately activated intrarenal RAS, is underscored." (PMID 31237175, 2019). "This form of angiotensinogen is the predominant form identified in patients with preeclampsia." (PMID 23557166, 2013). "This suggests that human REN produced by the paternal gene in the placenta may enter the maternal circulation and interact with maternal AGT to increase the expression of symptoms of preeclampsia." (PMID 20537141, 2010). "In contrast, the child's REN haplotypes A-t-C and c-G-t did not affect the mother's risk of preeclampsia, and neither did the child's AGT haplotypes C-T-A, C-c-g or t-c-g (data not shown)." (PMID 20537141, 2010). "The paradox between overexpression of renin and angiotensinogen creating preeclampsia-like symptoms in mice and the reduced levels observed in humans with preeclampsia suggests that renin-angiotensin-aldosterone system may be a downstream effect of other dysregulated systems." (PMID 37089425, 2023). "Another “risk factor” in development of preeclampsia, namely the SNP M235T (rs699) in the AGT gene, which is associated with increased levels of AGT, could contribute to the hypertensinogenic profile of preeclampsia because intrarenal production of Ang II would be enhanced." (PMID 31551925, 2019).